CX3CR1 (C-X3-C motif chemokine receptor 1)
Diseases named in the same sentence as CX3CR1 in open-access papers (continued):
Sharing a sentence is not in itself a finding about the gene and the disease.
tumor (continued). "In the E0771-mCherry-sGRP78 group, CX3CR1+ cells migrated to the tumor periphery with a mean velocity of 7.350 ± 0.5245 μm/min (n = 175 cells)." (PMID 33133103, 2020). "Cancer cells that circulate in the blood can express CX3CR1, which allows them to adhere to mCX3CL1 in blood vessels and, consequently, to migrate to organs distant from the parent tumor." (PMID 32466280, 2020). "Amongst the differentially expressed genes, CD274 (PD‐L1) was downregulated in the Cx3cr1‐Rheb1Δ/Δ compared to Rheb1fl/fl GL261 tumours, further highlighting a reduced level of T‐cell inhibition via checkpoint inhibitors in the TME (Fig EV3C)." (PMID 32567735, 2020). "TGF-β has also a direct effect on NK cells by increasing the expression of miR-27a-5p in these cells, which causes a decrease in CX3CR1 expression, and thus, affects CX3CL1-dependent migration of these cells to the tumor niche." (PMID 32466280, 2020). "This heterogeneous group of cells includes monocytic myeloid-derived suppressor cells (Mo-MDSC) with high expression of CX3CR1, which allows them to accumulate in a tumor with a high expression of sCX3CL1." (PMID 32466280, 2020). "The density of macrophages/microglia (Cx3cr1+-cells) was strongly increased in the tumor bearing hemisphere." (PMID 32042342, 2020). "The lymphocyte fraction showed an increase in CD8 CTL (CD45+ CD3+ CD8+) and CD4 Th cells (CD45+ CD3+ CD4+) in the Cx3cr1‐Rheb1Δ/Δ tumours." (PMID 32567735, 2020). "Only six tumors presented upregulation of CX3CR1 mRNA, compared to control (fold-change >2, p < 0.05), including a CX3CL1-mutated tumor (HB32)." (PMID 32432034, 2020). "While no histological differences were noted between the two genotypes, the numbers of GL261 GFP+ tumour cells were lower in the Cx3cr1‐Rheb1Δ/Δ tumours, consistent with the reduced tumour volume observed by MRI." (PMID 32567735, 2020). "Consistent with the low expression of CX3CR1 mRNA in human TRM cells, CX3CR1 expression was remarkably downregulated in CD8+ TILs in the macaque tumour model." (PMID 32439888, 2020). "This revealed a shift in the TAM population in the Cx3cr1‐Rheb1Δ/Δ tumours, with a significant decrease in TAM‐MG (CD45+ P2RY12+ CD49d−), while significantly higher numbers of TAM‐BMDM (CD45+ P2RY12− CD49d+) were observed." (PMID 32567735, 2020). "Another reason for the increase in CX3CR1 expression in a tumor is an increase in the expression of this protein on a tumor cell." (PMID 32466280, 2020). "In contrast, CX3CL1/CX3CR1 has been proven to induce tumor growth, proliferation, and apoptosis resistance through activating the AKT/NF-κB and JAK/STAT signalling pathways in PDAC." (PMID 31991604, 2020). "In our CX3CR1-GFP liver metastasis mouse model, tumor-secreted GRP78 was taken up by both F4/80+CX3CR1+ and F4/80–CX3CR1+ cells." (PMID 33133103, 2020). "Four days after tumor cell inoculation, the motility of CX3CR1+ cells in the E0771-mCherry-sGRP78-bearing mice was significantly increased." (PMID 33133103, 2020). "It has been shown that CX3CR1+ monocytes are recruited to the tumor cell aggregates in response to tumor-derived CX3CL1, where they can directly engage cancer cells or secrete CCL3, CCL4 and CCL5 to activate natural killer cells to kill CTCs." (PMID 33414786, 2020). "We found that tumor-secreted GRP78 reshaping the hepatic microenvironment by recruiting CX3CR1+ myeloid cells." (PMID 33133103, 2020). "IL-2 upregulates chemokine receptors such as CCR1 and CX3CR1, and thus stimulates NK cells migration to the tumor site." (PMID 33260925, 2020). "Another important issue is the effect of CX3CR1 expression in a tumor on the prognosis of cancer patients." (PMID 32466280, 2020). "It was shown that infiltrating Ly6Clow monocytes detect tumor through CX3CR1 and were capable of phagocytosing tumor material." (PMID 31402908, 2019). "We isolated the CX3CR1+NK cells from human HCC tissues to better reflect the real tumor environment." (PMID 31367257, 2019).
tumor (continued). "A possible involvement of CX3CR1 in the cross talk between neoplastic B cells and the tumor microenvironment has been proposed since CX3CL1 and CX3CR1 are co-expressed on different types of B malignant cells." (PMID 30845779, 2019). "CX3CL1 activates the SRC/focal adhesion kinase (FAK) signaling pathway in cancer cells regulating their migration and invasion and facilitates bone metastasis of CX3CR1-expressing tumor cells." (PMID 30845779, 2019). "The average tumor size and pulmonary metastasis rate were decreased in mice treated with CX3CR1+ NK cells alone relative to those treated with CX3CR1+NK cells combined with an anti-CX3CL1 antibody or an anti-CX3CR1 antibody." (PMID 31367257, 2019). "Similar results were also found with SKBR7 tumour xenografts when monocytes were treated with an anti-CX3CR1 antibody in vitro prior to adoptive transfer." (PMID 29367702, 2018). "In our in vivo data, tumor burden at the omentum was significantly reduced by downregulation of CX3CR1 and its combination with radiation." (PMID 29712888, 2018). "On the other hand, CX3XL1/CX3CR1 signaling axis transduces pro-survival, proliferative and metastatic signals, favoring tumor progression." (PMID 29867042, 2018). "CX3CR1 genetically modified T cells transferred into CX3CL1 producing colorectal adenocarcinoma tumor bearing mice displayed enhanced tumor infiltration and anti-tumor responses." (PMID 30420855, 2018). "Our preclinical animal model studies also demonstrate that that CIT combination after previous exposure to immunotherapy provides better tumor control with an increase in CX3CR1+CD8+ T cells population." (PMID 30100909, 2018). "The CX3CL1 expressed by GB cells induces the human GAMs recruitment through its receptor CX3CR1 and increases the expression of matrix MMPs 2, 9, and 14 in GAMs, which consequently promotes the tumor invasion." (PMID 30123112, 2018). "Transient downregulation of CX3CR1 alone significantly reduced tumor burden, while irradiation alone almost completely obliterated tumor burden at the liver." (PMID 29712888, 2018). "The double-mutant mice allowed us to compared not only tumor-bearing mice with healthy subjects, but also mice with a different tumor-load, due to the CX3CR1-dependent phenotype." (PMID 30140377, 2018). "For the small intestine tumor model, independently from the CX3CR1 status, APC+/min and WT mice were shaved and injected, 24 h before the acquisition, with 0.08 nmol/g of body weight of IntegriSense750 probe after 14 and 18 weeks of age." (PMID 30140377, 2018). "Together, these data indicate that transient downregulation of CX3CR1 and x-ray radiation alone as well as their combination affect tumor formation in an organ-specific manner." (PMID 29712888, 2018). "Irradiation and downregulation of CX3CR1, either alone or in combination with each other, affected tumor formation at intraperitoneal organs covered by visceral peritoneum as well as at retroperitoneal organs." (PMID 29712888, 2018). "We have further specified this phenotype with the use of additional markers CCR2 and CX3CR1 which allowed us to define a specific population, induced in our tumor model and to give a hint towards possible immune regulation." (PMID 28744322, 2017). "CX3CR1 expression also has a pivotal role in tumors, conditioning migration and adhesion of tumor cells, and tumor invasiveness and metastasis." (PMID 28791023, 2017). "The fractalkine/CX3CR1 axis has been proposed to increase the metastasis of prostate cancer and tumor growth in epithelial ovarian cancer by activating Akt signaling." (PMID 28903329, 2017). "Conversely, inactivation of CDKs by chemical inhibitors increases the expression of CX3CR1 in Mo-MDSCs, resulting in accumulation of Mo-MDSCs in tumours and consequent acceleration of tumour growth in allograft mouse models." (PMID 29234059, 2017). "In particular, it decreases the expression of CX3CR1 that drives these effectors toward peripheral tissues, including tumor sites." (PMID 28791023, 2017).
tumor (continued). "The growth of SCT-LT was substantially increased in mice treated with flavopiridol, accompanied by enhanced CX3CR1 expression in Mo-MDSCs and increased accumulation of Mo-MDSCs in tumours." (PMID 29234059, 2017). "Both p16Ink4a and p21Cip1/Waf1 are expressed in Mo-MDSCs and facilitate infiltration of Mo-MDSC into the tumour microenvironment by upregulating CX3CR1 expression and conferring resistance to anti-tumour immune mechanisms." (PMID 29234059, 2017). "CD11b+CX3CR1+ monocytes are a subpopulation of CD11b+Gr1+ cells that were shown to be myeloid-derived suppressor cells (MDSCs) in mouse tumor models." (PMID 29190915, 2017). "Previous studies have indicated that the fractalkine/CX3CR1 axis promotes tumor progression by activating PI3K/Akt signaling." (PMID 28903329, 2017). "The biological effects of fractalkine are mediated through its receptor CX3CR1 which is widely expressed on different cell types including monocytes/macrophages, NK cells, cytotoxic T cells, B cells, smooth muscle cells, tumor cells, microglia, and neurons." (PMID 28396851, 2017). "For this we implanted red fluorescent protein-expressing tumor cells in brain slices from CX3CR1-GFP mice." (PMID 26673818, 2016). "The FACS analysis obtained from four distinct mice showed significantly higher infiltration of CD3+ and CX3CR1+ lymphocytes in tumors of each mouse receiving CX3CR1-T lymphocytes, confirming their preferential tumor homing ability." (PMID 27096098, 2016). "The adoptive transfer of CX3CR1-transduced T cells in tumor-bearing mice indeed resulted in improved homing towards Fractalkine-expressing tumors." (PMID 27096098, 2016). "This GL261/CX3CR1 model allowed analysis of microglia morphology during tumor growth and morphometrical measure of parameters of microglia activation in tumor areas." (PMID 26856327, 2016). "The concordant upregulation of fractalkine and other chemokines in the tumour and CX3CR1 on CD8+ T cells on-treatment suggest a mechanism for the increased tumour infiltration of CD8+ T cells." (PMID 27571927, 2016). "Mice were subcutaneously inoculated with NCI-H630 tumor cells and checked for tumor development; after 18 days, eGFP or CX3CR1-eGFP lymphocytes (3 × 106) were transferred through tail vein injection." (PMID 27096098, 2016). "Our data thus support a role for CX3CR1+ SCS macrophages in the uptake of subcellular-sized tumor-derived material presumably from apoptotic tumor cells, in line with previous observations." (PMID 25821451, 2015). "Taken together, our results provide insights into the differences in CX3CR1 signaling in microglia versus bone marrow-derived “inflammatory” monocytes, which includes migration and tumor-promoting effects." (PMID 25987130, 2015). "First, we showed that the loss of CX3CR1 signaling in the host microenvironment results in increased GBM formation and shortened tumor latency." (PMID 25987130, 2015). "These tdTom+ structures were typically in close apposition to or inside of CX3CR1+ macrophages in the SCS of the tumor-draining popliteal LNs." (PMID 25821451, 2015). "Tumor cells from PDAC patients strongly expressed CX3CR1 that mediates migration to CX3CL1 constitutively expressed by neural cells." (PMID 24799766, 2014). "As apparent from this review, the CX3CL1/CX3CR1 axis promotes inflammation and tumor growth in the majority of disease models discussed." (PMID 24799766, 2014). "DLBCL, FL, MCL, and MALT lymphoma were found to express CX3CR1 at mRNA and protein levels suggesting a functional role for this receptor in the interaction between lymphoma cells and tumor microenvironment." (PMID 24799766, 2014). "Normal and malignant breast tissues express CX3CR1 but its overexpression increases the ability of tumor cells to migrate to skeleton and brain where bone stromal cells and neurons release soluble CX3CL1." (PMID 24799766, 2014).
tumor (continued). "Taken together, these results suggested that CX3CR1 was necessary for TAMs-induced angiogenic responses during tumor development." (PMID 24245985, 2013). "In the present study, especially we demonstrated the role of CX3CR1 in regulating tumor inflammatory microenvironment." (PMID 24245985, 2013). "Mechanistically, CX3CR1 signaling was critical for survival of angiogenic macrophages and promoting tumor angiogenesis." (PMID 24245985, 2013). "Our results suggest a role of CX3CR1 in angiogenic macrophage survival in the tumor microenvironment contributing to tumor metastasis." (PMID 24245985, 2013). "As numerous attempts are ongoing to target the tumor stroma, we propose CX3CR1 as a potential molecular target for antiangiogenic and antimetastatic cancer therapy." (PMID 24245985, 2013). "This work highlights the function of CX3CR1 in the tumor inflammatory response and identifies CX3CR1 signaling as the important player in the complex interactions between tumor cells and the tumor microenvironment." (PMID 24245985, 2013). "Taken together, these data suggested that CX3CR1 contributed to macrophages survival and promoting angiogenesis in the tumor microenvironment." (PMID 24245985, 2013). "The present work elucidated CX3CR1 mediates survival of macrophage, promoting angiogenesis leading to tumor metastasis." (PMID 24245985, 2013). "Analysis of MC38 tumor-bearing mice treated with the Bpmel-SIY-OVAII cell adjuvant revealed a sustained increase in the proportion of CD27− CX3CR1+ and CD62L− CD44+ effector CD8+ T cells in the DLN as well as more significant infiltration of CD8+ T cells in the tumor site." (PMID 41348109, 2026). "In the field of cancer immunotherapy, CAR-T cells engineered to co-express CX3CR1 (NKG2D-CX3CR1 CAR-T) have been shown to enhance tumor infiltration and antitumor efficacy, demonstrating robust therapeutic effects, especially in tumor models with high CX3CL1 expression." (PMID 40508161, 2025). "These monocytes highly express the proinflammatory chemokine receptor CX3CR1 and, upon stimulation with nucleic acids derived from apoptotic tumor cells (via TLR8 agonists), produce cytokines such as TNF-α, IL-6, and CCL3, which are known to promote MM cell proliferation." (PMID 40508161, 2025). "Overall, these receptor cells involved in paracrine signaling exert weaker tumor-killing effects than CX3CR1+ NK/T cells, and they may exhibit more complex and diverse regulatory." (PMID 40474982, 2025). "As we found CX3CR1 expression in the tumour cells of the mouse model as well as high levels of CX3CL1 in peritoneal metastases of the HGSOC cohort, we agree that the receptor may play an important role for the overall negative outcome in survival." (PMID 39862711, 2025). "In summary, the present study demonstrated that both DAC and 5-FU promoted the differentiation of stem-like CD8+ TTSM cells in TdLNs and significantly enhanced the differentiation and expansion of stem-like CD62L+CD8+ Tpex and CX3CR1+ Texint cells in tumor microenvironment." (PMID 40236705, 2025). "Similarly, expression of the microglia homeostatic genes P2RY12 and CX3CR1 declined with tumor grade, while expression of the immunosuppressive genes IL10 and F11R (JAM-A) increased with tumor grade." (PMID 38895459, 2025). "Through transcriptomic sequencing analysis of tumours in WT and ApoE−/− mice, we observed that ApoE deficiency resulted in decreased expression levels of the immunologically relevant genes CCL24, CD74, and CX3CR1." (PMID 40662483, 2025). "The present study demonstrated that both DAC and 5-FU promoted the differentiation of stem-like CD8+ TTSM cells in TdLNs and significantly enhanced the differentiation and expansion of stem-like CD62L+ CD8+ Tpex and CX3CR1+ Texint cells in tumor microenvironment." (PMID 40236705, 2025). "We therefore hypothesise that tumour cell-tumour cell or tumour cell-mesothelial cell interactions through the CX3CL1/CX3CR1 system may be responsible for the tumour-promoting effect." (PMID 39862711, 2025).
tumor (continued). "Therefore, we infer that the self-secretory ability of PGD2 is strongly correlated with the cytotoxicity and tumor-killing capacity of CX3CR1+ NK/T cells." (PMID 40474982, 2025). "Given the relatively high expression of FKN in spinal cancellous bone, CX3CR1-expressing metastatic tumor cells may be attracted." (PMID 38731899, 2024). "The explanation for the efficacy of the immune response related to the FKN/CX3CR1 axis in various types of cancers (anti-tumor response) or lead to disease progression (pro-tumor response) is related to the presence of two forms of FKN: membrane-bound and soluble FKN." (PMID 38731899, 2024). "However, the expression of TNFα and IFNγ in the CX3CR1+ subset was substantially lower than the CX3CR1− subset in the tumor." (PMID 38881188, 2024). "The Hom-MG-1 subgroup highly expressed the innate characteristic genes of microglia (Tmem119, P2ry12, Crybb1, Cst1, Gpr34, and Cx3cr1), poorly expressed tumor activation-related genes, and expressed early activation genes to a certain extent (Jun, Junb, Jund, and Fos)." (PMID 39867913, 2024). "The homing of these cells to the TME may be enhanced by increasing CX3CR1 expression and/or increasing sFKN expression in the tumor." (PMID 38731899, 2024). "The chemokine axis CX3CR1/CX3CL1 plays a critical role in adhesion between tumor cells and nerves." (PMID 39402303, 2024). "CX3CR1 was also found to be a marker of T-cell differentiation, where functionally distinct viral and tumor-specific CX3CR1− CD8+ T cells expressing high levels of TCF-1, CD62L, CD27, and/or CD127 can give rise to CX3CR1+ subsets via unidirectional differentiation upon activation in vivo." (PMID 38881188, 2024). "Notably, CX3CR1+ macrophages enriched NR5A1+ tumor cells and INHBA-ACVR1B were locationalized closely in the spatial transcriptome of SF1 lineage tissue." (PMID 38658971, 2024). "Mainly, CX3CR1+ macrophages may hold significant promise in regulating tumor angiogenesis and inflammation." (PMID 38658971, 2024). "While the role of the fractalkine/CX3CR1 signaling axis was described in the nervous system and was also related to the migration of leukocytes to sites of inflammation, its actions are controversial in cancer progression and anti-tumor immunity." (PMID 39125578, 2024). "In contrast with these studies, nonclassical “patrolling” monocytes, which are enriched in the microvasculature of the lung in a CX3CR1-dependent manner, interact with metastasizing tumor cells, scavenge tumor material from the lung vasculature, and promote NK cell recruitment and activation." (PMID 39402303, 2024). "The recruitment of circulating CX3CR1+ monocytes is critical for tumor angiogenesis." (PMID 38731899, 2024). "The transient or tumor-specific activity of ADAM10 or TACE/ADAM17 may play a key role because changing the mFKN/sFKN ratio modifies the signaling of the FKN/CX3CR1 axis to reveal anti- or pro-tumor effects." (PMID 38731899, 2024). "CX3CR1+ T-cell subsets can be identified in tumors; however, it remains unclear whether they migrate from secondary lymphoid organs via the CX3CR1/CX3CL1 axis or directly differentiate from CX3CR1− CD8+ T cells in the tumor microenvironment." (PMID 38881188, 2024). "Thus inflammatory precursors from PBMC expressing CXCR1, CXCR3 and CX3CR1 selectively enter inflamed tumor tissues." (PMID 38390333, 2024). "Moreover, the connection between CX3CR1+ macrophages and tumor cells via INHBA-ACVR1B regulates tumor cell apoptosis." (PMID 38658971, 2024). "Although CX3CR1+ CD8+ T cells are present in tumors, it remains unclear whether they directly differentiate from the CX3CR1− subset within the tumor microenvironment or are trafficked from secondary lymphoid organs via the CX3CL1/CX3CR1 chemokine axis." (PMID 38881188, 2024). "To test this premise, we examined whether PARPis could synergize with the loss of CX3CR1 in (a) reducing clone formation in HGSOC cell lines and (b) reducing tumor growth in xenograft mouse models." (PMID 39594684, 2024).